IL4 (interleukin 4)
Diseases named in the same sentence as IL4 in open-access papers (continued):
Sharing a sentence is not in itself a finding about the gene and the disease.
liver fibrosis (continued). "While the present study has supplied much useful information about the predictive value of IP-10 and the IFN-γ/IL-4 ratio in the liver fibrosis of CHB patients, it has several limitations that must be acknowledged." (PMID 28067328, 2017). "IFN-γ, which has been found to play roles in both liver fibrosis and inflammatory reaction, was elevated more than IL-4 in the early stages of liver fibrosis." (PMID 28067328, 2017). "In accordance with the smaller granuloma size and less extensive hepatic fibrosis in group f/mf at week 19, lower serum cytokine levels of pro-fibrotic IL-4 and IL-13 were measured." (PMID 28542175, 2017). "We also calculated the ratio of IL-4/IFN-γ, and examined the correlation between the ratio of IL-4/IFN-γ with the degree of liver fibrosis, and the resulting data supported the current conclusion as made using the IFN-γ/IL-4 value." (PMID 28067328, 2017). "The difference in the IFN-γ/IL-4 ratio between any two liver fibrosis groups of CHB patients was statistically significant (P < 0.05)." (PMID 28067328, 2017). "Compared to the controls (F0 group), IP-10, IFN-γ, and IL-4 protein expression increased with advancing stages of liver fibrosis, and the highest levels of these proteins were found in the F5–6 group, which was consistent with the mRNA analysis results." (PMID 28067328, 2017). "In contrast, IL-4, which is closely related to the injury-repair process and the accumulation of extracellular matrix proteins, plays a critical role in accelerating liver fibrosis by inducing collagen production via an IL-4Rα-STAT6-depentent mechanism." (PMID 28067328, 2017). "Whereas the IFN-γ/IL-4 ratio gradually declined with increasing stages of liver fibrosis in the CHB patients, although the mRNA and protein levels of IFN-γ and IL-4 each alone were increased." (PMID 28067328, 2017). "The Th-1 immunity profile (IL-2, IL-12, TNF-α, and IFN-γ) is correlated with liver fibrosis in patients with chronic hepatitis C, whereas Th2 immunity profile (IL-4 and IL-10) cannot control viral clearance." (PMID 27413763, 2016). "Th2 cytokines IL-4, IL-5 and IL-13 are dramatically increased in liver fibrosis with IL-13 being an indispensable mediator of fibrosis." (PMID 26771187, 2016). "Regardless the liver fibrosis score, this direct correlation between IL-4 and IL-17 axes is preserved." (PMID 26742960, 2016). "For instance, increased levels of IL-4 were detected in patients with IPF or cryptogenic fibrosing alveolitis; and inhibition of IL-4 by neutralizing antibodies or inhibitors reduced liver fibrosis and dermal fibrosis in mice." (PMID 27814727, 2016). "Out study showed that treatment with anti-IL-9Ab and anti-IL-17Ab exerted similar effects on suppressing plasma secretion and liver expression of TGF-β1, IL-6, TNF-α, IL-4 and IL-9 in mice with liver fibrosis." (PMID 26728971, 2016). "Cytokines involved in liver fibrosis, such as IL-4 or IL-33, act as chemoattractants, driving the activation of mast cells." (PMID 24839609, 2014). "In hepatic fibrosis, the level of IL-4, which is responsible for promoting collagen synthesis, were higher in the susceptible mice than in the mice that were resistant." (PMID 24294831, 2013). "Additionally, Interleukin-4 (IL-4), Interleukin-22 (IL-22) exerts both anti-inflammatory and pro-inflammatory roles in liver fibrosis." (PMID 39995661, 2025). "Moreover, in C57BL/6 mice infected with Schistosoma japonicum, liver fibrosis is associated with enhanced phosphorylation of STAT6, in accordance with the hepatic upregulation of IL-4 and IL-13 receptors." (PMID 41409600, 2025). "Finally, we examined the therapeutic effect of human IL-34 + IL-4 Mf in a liver fibrosis model using immunodeficient NSG mice in which human PBMCs had been administered (see the Methods section)." (PMID 39856797, 2025). "Moreover, IL-4 can act directly on HSCs to promote their proliferation, increase collagen production, and accelerate the progression of liver fibrosis." (PMID 39995661, 2025).
liver fibrosis (continued). "Furthermore, melatonin has been shown to attenuate thioacetamide-induced liver fibrosis in male rats by modulating IL-6, IL-4, apoptosis, and urokinase-type plasminogen activator receptor-related protein/Endo180 expression." (PMID 39995661, 2025). "Besides suppressing hepatic stellate cells, IL-34 + IL-4 Mfs significantly suppressed liver parenchymal cell damage and T cell activation, which is upstream of the liver fibrosis process." (PMID 39856797, 2025). "Next, we investigated whether treatment with the alternatively activated Mf induced by IL-34 + IL-4 was also effective in liver fibrosis models." (PMID 39856797, 2025). "Therefore, it is possible that Stat6 similarly regulates the phenotype and function of IL-34 + IL-4 Mf in the treatment of liver fibrosis at the transcription factor level." (PMID 39856797, 2025). "NKT cells can exacerbate hepatic fibrosis by producing IL-4 that induces GARP expression on HSCs." (PMID 40761743, 2025). "Liver fibrosis was significantly inhibited with the IL-34 + IL-4 Mf treatment." (PMID 39856797, 2025). "Notably, it has been shown that infusion lipopolysaccharides (LPS) and interferon‐γ (IFN‐γ) treated macrophages are more efficient than untreated macrophages or IL‐4‐induced macrophages in alleviating liver fibrosis." (PMID 38247166, 2024). "Recent studies suggest that macrophages switched to the M1 phenotype exert pro-inflammatory as well as pro-fibrogenic roles in the pathogenesis of liver fibrosis, while macrophages polarized to M2 phenotype responding to the stimulation of IL-4 or IL-13 attenuate the progression of liver fibrosis." (PMID 37760020, 2023). "On the other hand, NKT cells might promote the progression of hepatic fibrosis through production of the type 2 profibrotic cytokines IL-4 and IL-13." (PMID 37817226, 2023). "We previously revealed that CsTPs could promote the production of Th2 cytokines, including IL-13 and IL-4, both in vitro and in vivo, and ultimately resulted in the development of liver fibrosis." (PMID 36510325, 2022). "IL-4 and IL-6 have shown a potent protective effect on liver fibrosis." (PMID 36544761, 2022). "The production of IL-4 induced by F. gigantica infection could promote tissue repair and further liver fibrosis." (PMID 35071045, 2021). "Moreover, blockade of IL-4 or IL-13 inhibits the effects of NKT cells on upregulating α-SMA in HSCs in vitro, suggesting that NKT cells promote liver fibrosis via Th2 cytokines in HBV-associated liver fibrosis." (PMID 32708044, 2020). "However, Tenericutes, Deferribacteres, and Firmicutes negatively related with liver fibrosis, IL-4 and IFN-γ." (PMID 32295161, 2020). "Th2 cytokines, mainly IL-4 and IL-13, had distinct roles in the regulation of liver fibrosis." (PMID 29505573, 2018). "It was reported that Th1 cytokines suppress liver fibrosis, with interferon-γ being a potent inhibitor of the activation of hepatic stellate cells, while Th2 cytokines such as IL-4 and IL-3 promote activation of hepatic stellate cells and progression of liver fibrosis." (PMID 30116748, 2018). "Moreover, the mRNA levels of IP-10, IFN-γ, and IL-4 increased the most in the F5–6 group, and there was a trend toward higher mRNA levels with the degree of liver fibrosis." (PMID 28067328, 2017). "Thus, our findings add an important serum marker, either alone or in combination with the IFN-γ/IL-4 ratio, to predict significant liver fibrosis induced by HBV infection." (PMID 28067328, 2017). "Therefore, mechanisms of liver fibrosis inhibition by IL-34 + IL-4 Mf may function in a complex manner at multiple points." (PMID 39856797, 2025). "The enzyme HGPRT could reduce the physiopathological aspects that lead to related morbidity, such as liver fibrosis and positive modulation for IL-4 and IgE expression, while the enzyme PNP showed effect on the worm itself, reducing the parasitic load and number of eggs." (PMID 37111413, 2023).
liver fibrosis (continued). "Similarly, bone marrow MSCs transplantation can alleviate liver fibrosis by promoting the phenotypic shift of monocytes from the pre-fibrotic Ly6Chi subpopulation to the restorative Ly6Clow subpopulation through paracrine secretion of IL-4 and IL-10." (PMID 35895169, 2022). "Moreover, the IL-4/STAT6 activation could regulate liver fibrosis and cardiac fibrosis progression through targeting macrophages." (PMID 35784347, 2022). "Infected mice treated with ginger Cs Nps 500 mg/kg possessed a lessening in the IL-4 and IL-10 levels, which agreed with the report stating that ginger extract declined the inflammation mediators that have a marked contribution in schistosomal-liver fibrosis and its consequences." (PMID 36362992, 2022). "Genistein protected against liver fibrosis caused by S. japonicum and decreased the extent of hepatic granuloma via inhibiting activation of NF-κB signaling pathway and led to downregulation of inflammatory cytokines MCP1, TNFα, IL1β, IL4, IL10 in infected mice." (PMID 32410640, 2020). "In this paper, our findings indicate that CHB patients have an imbalanced IFN-γ/IL-4 ratio and that Th1/Th2 cytokines drift into a Th2 lymphocyte subcluster with the degree of liver fibrosis, suggesting that the imbalance of IFN-γ/IL-4 may be involved in the immunopathogenesis of CHB fibrosis." (PMID 28067328, 2017). "In addition, interleukin (IL)-4, which is closely related to the injury-repair process and accumulation of extracellular matrix proteins, plays a critical role in accelerating liver fibrosis by inducing collagen production via an IL-4Rα-STAT6-dependent mechanism." (PMID 28067328, 2017). "Rutin significantly reduces serum TNF-α, IL-17, and IL-4 in S. mansoni infection, aligning with prior studies on TFL’s suppression of Schistosoma japonicum (S. japonicum)-induced liver fibrosis." (PMID 40809521, 2025). "It has been shown that the IL-4/STAT6 and IL-13/STAT6 signaling pathways exacerbate the progression of metabolically induced liver fibrosis in mice on HFD." (PMID 41409600, 2025). "In the prevention and treatment of skin and liver fibrosis, CBD inhibited collagen gene transcription and synthesis and prevented TGF-β and IL-4 induced fibroblast migration." (PMID 38711461, 2024). "For instance, mouse-derived mmu-miR-92a-2-5 can target TLR2 to inhibit Schistosoma japonicum-induced liver fibrosis and downregulate the expression of TLR2-related cytokines such as IL-4, IFN-γ, and TNF-α during S. japonicum infection in mice." (PMID 37559722, 2023). "IL-4 and IL-13 from activated NKT cells promote liver fibrosis, suggesting a role for NKT cells in cirrhosis resulting from chronic autoimmune liver injury." (PMID 36389715, 2022). "CD4+ memory static T cells secrete iconic cytokines IL-4, IL-10, and IFN-G, and stimulate other immune cells such as NK cells, to media the progress of liver fibrosis." (PMID 36686655, 2022). "As regards hepatic fibrosis, our results showed that cases of post-hepatitis fibrosis of high scores (F3 and F4) showed higher degrees of IL-4, IL-17, and CD163 expression, compared to low scores of hepatic fibrosis (F1 and F2)." (PMID 33906302, 2021). "Type 2 immune response characterized by type 2 cytokines plays an important role in liver fibrosis as IL-4, IL-13, and TGF-β1 produced by macrophages can activate HSCs leading to liver fibrosis." (PMID 34733286, 2021). "Above results showed that liver fibrosis (P = 0.008), IFN-γ (P = 0.004) and IL-4 (P = 0.003) all significantly influenced the bacterial community structures at the genus level." (PMID 32295161, 2020). "Chronic stimulation of anti‐inflammatory (IL‐4, IL‐10, IL‐13 and TGF‐β1) factors is related to liver fibrosis progression." (PMID 31755616, 2020). "In contrast to the type 2 cytokine IL-4 signaling as a pro-fibrotic mediator, IFN-γ has been characterized as an anti-fibrotic cytokine in the context of CCl4-mediated liver fibrosis." (PMID 33178216, 2020).
liver fibrosis (continued). "Furthermore, the IP-10 level in combination with the IFN-γ/IL-4 ratio had a sensitivity of 86.9%, a specificity of 93.8%, a positive predictive value of 94.6%, and a negative predictive value of 84.9% for the prediction of significant liver fibrosis in CHB patients." (PMID 28067328, 2017). "Anti-IL-9Ab treatment sharply decreased plasma concentrations of TGF-β1, IL-6, IL-4, and TNF-α in a mouse model of liver fibrosis." (PMID 26728971, 2016). "We further examined the role of the endogenous IL-9 in hepatic fibrosis and its relationship with other relevant cytokines, including IL-17A, IFN-γ, TGF-β1, IL-6, IL-4, IL-21 and TNF-α in response to hepatic fibrosis, by neutralizing IL-9 in a mouse model." (PMID 26728971, 2016). "The global cytokine surveys of HSC-CM have demonstrated that TNF-α, agrin, PDGF, activin A, GM-CSF, IFN-γ, IL-1β, IL-4, IL-6, IL-10, IL-13, and TIMP-1, which subsequently induce acute inflammation and liver fibrosis, were elevated in aHSC-CM relative to the qHSC-CM." (PMID 36142683, 2022). "IL-4 has shown an anti-fibrotic effect, by activating alternatively activated macrophage, M2, which breakdown extracellular matrix (ECM), leading to resolution of liver fibrosis, by secreting matrix metalloproteinase-12 (MMP-12)." (PMID 36544761, 2022). "MSCs could also promote mobilization of Kupffer cells in vitro and in vivo and induce M1 to M2 conversion by increasing IL-4 and IL-10 secretion, thereby alleviating dimethylnitrosamine (DMN)-induced liver fibrosis." (PMID 35895169, 2022). "Thus, critical roles for IL-33 in activation of Th2 immune responses via cytokines IL-4, IL-6 and IL-13 have been demonstrated in the pathogenesis of HSEC proliferation and liver fibrosis in mouse models." (PMID 32486265, 2020). "Elevated levels of IP-10, IFN-γ, IL-4, and TGF-β1 were detected in the CHB patients with liver fibrosis (F1–2, F3–4, and F5–6), compared to the controls (F0), and there was a trend toward greater levels of IP-10 with an increasing degree of liver fibrosis." (PMID 28067328, 2017). "However, in the late stage of liver fibrosis or liver cirrhosis, IFN-γ increased less than IL-4, which led to the lower ratio of IFN-γ/IL-4 in the F5–6 group versus the F1–2 and F3–4 groups." (PMID 28067328, 2017). "Next, we performed experiments using quantitative immunohistochemistry to examine hepatic IP-10, IFN-γ, and IL-4 protein expression in CHB patients with or without liver fibrosis." (PMID 28067328, 2017). "Neutralization of IL-9 further suppressed expression of inflammatory cytokines including IL-9, IL-17A, IFN-γ, TGF-β1, IL-6, IL-4 and TNF-α in the mouse model of hepatic fibrosis, suggesting IL-9 may regulate the inflammatory responses to liver fibrosis." (PMID 26728971, 2016). "Although several studies have focused on the contribution of Th2 cells to chronic inflammatory disease and fibrosis, which is characterized by the cytokines IL-4 and IL-13, CD4+ IL-17-secreting T cells have been shown to contribute to pathology in some models of liver fibrosis." (PMID 25590646, 2015). "Besides, gene expressions of Th1/Th2 cytokines such as IL-4, IL-10, IL-13 and IFN-γ, which were important in schistosomiasis liver fibrosis, were also detected in our experiment." (PMID 21629648, 2011). "Thus, in contrast to the enhanced liver toxicity observed in IL-4−/−, IL-4Rα−/−, and LysMCreIL-4R−/− mice, CAT2−/− mice developed significant liver fibrosis, portal hypertension, and collateral vessels, which are features of severe hepatosplenic disease." (PMID 18369473, 2008). "Neutralization of IL-9 in mice ameliorated hepatic fibrosis, attenuated the activation of hepatic stellate cells, reduced frequencies of Th9, Th17 and Th1 cells in spleen, and suppressed expression of IL-9, IL-17A, IFN-γ, TGF-β1, IL-6, IL-4 and TNF-α in plasma and liver respectively." (PMID 26728971, 2016).
liver fibrosis (continued). "We examined the levels of serum IP-10, IFN-γ, IL-4, and transforming growth factor (TGF)-β1 in CHB patients with or without liver fibrosis by ELISA." (PMID 28067328, 2017).
tuberculosis (74 papers, 2006 to 2026). A chronic, recurrent infection caused by the bacterium Mycobacterium tuberculosis. "The shorter ncVNTR has been associated with reduced IL4 expression and increased susceptibility to tuberculosis, whereas the longer allele enhances IL4 transcription and promotes a Th2-skewed autoimmune response, advantageous in parasite-rich environments." (PMID 41437782, 2026). "Pooled analysis of respiratory infections revealed a significant association with the rs2070874 of the IL4 gene and additional genetic risk factors for tuberculosis." (PMID 32917282, 2020). "Through the literature search, we found that interleukin gene is related to the occurrence of tuberculosis, few studies have explored the association between IL4, IL6, and IL10 polymorphisms and PTB risk in Chinese populations." (PMID 29662655, 2018). "In experimental models, some studies have shown an association of increased IL-4 with progression of tuberculosis and reactivation of the disease, but other authors have shown that the absence of this cytokine does not influence susceptibility to the disease." (PMID 26495323, 2015). "An association between increased IL-4 production and progression of tuberculosis has been demonstrated in experimental models, although the absence of this cytokine does not influence the susceptibility to disease." (PMID 23824716, 2013). "Pulmonary cavitation in tuberculosis is known to be associated with the production of Th2 cytokines such as IL-4, which have in turn been demonstrated to result in higher surface expression levels of DC-SIGN in DCs." (PMID 18167547, 2008). "Previous studies showed that the level of IL-4 in tuberculosis patients was decreased, suggesting that IL-4 may be associated with the development of tuberculosis." (PMID 38047067, 2023). "In tuberculosis patients, it is believed that the expression level of IL-4 and its splicing variant might be associated with tuberculosis infection and chest radiographic patterns." (PMID 29433383, 2018). "Some cytokines resulting from the activation of T lymphocytes and phagocytic cells, such as IFN-γ and TNF-α, are efficient in controlling infection, while others may contribute to the survival and growth of Mtb or mediate susceptibility to tuberculosis, including IL-4, TGF-β, and IL-10." (PMID 37892223, 2023). "Since high levels of IL-4 are correlated with tuberculosis (TB) susceptibility and progression, we investigated the role of DC-SIGN in M(IL-4) macrophages in the TB context." (PMID 29946317, 2018). "utilized machine learning techniques and found that among HIV-positive patients, those with tuberculosis exhibited significantly elevated levels of inflammatory markers including IL-2, IL-4, IL-6, IL-10, TNF-α, and IFN-γ." (PMID 41322408, 2025). "Associations varied by cause of death: tuberculosis-associated mortality was most strongly associated with higher CRP and sST2, and cryptococcosis-associated mortality with higher IL-4 and lower IL-8." (PMID 38944653, 2024). "The mRNA level of IL-4 expression was higher in unstimulated peripheral blood mononuclear cells of tuberculosis patients." (PMID 38675618, 2024). "The results depicted a considerably increased level of serum IL-4 in patients with tuberculosis than in the controls (standard mean difference [SMD] = 0.630, [95% confidence interval (CI), 0.162–1.092])." (PMID 37327256, 2023). "The present study aimed to evaluate the significance of IL-4 concentration in patients with tuberculosis." (PMID 37327256, 2023). "Th2 cytokines, i.e., IL-4, IL-6, IL-10, IL-13, etc., inhibit Th1 responses and thus cross-regulate and influence the progression to active tuberculosis." (PMID 36776550, 2022). "Th2 cells secrete cytokines such as interleukin 4 (IL-4), which play a role in downregulating the protective response to Th1 and increasing in advanced stages of tuberculosis." (PMID 35582059, 2022).